SETD2 (SET domain containing 2, histone lysine methyltransferase)
Diseases named in the same sentence as SETD2 in open-access papers (continued):
Sharing a sentence is not in itself a finding about the gene and the disease.
mesothelioma (13 papers, 2016 to 2026). A usually malignant and aggressive neoplasm of the mesothelium which is often associated with exposure to asbestos. "High-coverage multi-gene studies can not only confirm key molecular events described in single-gene studies, but also uncover less common features that may be driving mesothelioma development, such as the loss of tumor suppressor genes SETD2, PBRM1, and PTEN." (PMID 30060501, 2018). "Clonal positive selection (dN/dS>1) involved five tumour suppressors NF2, BAP1, SETD2 which were independently validated in the mesothelioma TCGA7, FBXW7 and PRELID1." (PMID 33741915, 2021). "For mesothelioma, the top genes with mutations were BAP1 (BRCA-associated protein 1), NF2 (neurofibromin 2), and SETD2 (SET domain containing 2, histone lysine methyltransferase)." (PMID 32033319, 2020). "Moreover, silencing of SETD2 or PBRM1 was found to increase proliferation in a mesothelioma cell line." (PMID 29371938, 2017). "TRAF7 was enriched in WDPMT, while common mesothelioma alterations (BAP1, NF2, CDKN2, and SETD2) were absent." (PMID 39167353, 2024). "The results revealed biallelic gene inactivation of SETD2, BAP1, PBRM1, and SMARCC1, suggesting that the mesothelioma genome is affected by minute deletions that are non-detectable by singular NGS-based approaches or commercial array CGH." (PMID 30060501, 2018).
osteosarcoma (13 papers, 2019 to 2025). A usually aggressive malignant bone-forming mesenchymal neoplasm, predominantly affecting adolescents and young adults. "Given the high amino acid conservation (91.8%) between human and canine SETD2, the observed mutations affect regions analogous to known mutation regions in human osteosarcoma." (PMID 40507962, 2025). "SETD2 gene, a histone methyltransferase and an important tumor-suppressor, was found to be mutated in 21% of canine osteosarcoma samples and showed a variety of mutation types including frameshift, nonsense, splice, and missense mutations." (PMID 33194754, 2020). "Another study detects SETD2 somatic point mutations, deletions, and chromosomal translocations in 42% of canine osteosarcoma samples." (PMID 33194754, 2020). "SETD2 is also recurrently mutated in whole-exome sequenced canine osteosarcomas, T-cell lymphomas, and diffuse large B-cell lymphomas." (PMID 32857815, 2020). "Subsequent WES on osteosarcoma-susceptible dogs indicated that osteosarcoma may originate from SETD2 mutations, which function as oncogenic drivers." (PMID 37359376, 2023). "SETD2 mutation in osteosarcoma can inhibit the growth of tumor cells." (PMID 32231741, 2020). "SETD2, a histone methyltransferase that functions as a tumor suppressor, is mutated in a variety of human cancers; however, somatic SETD2 mutations occur in <2% of human osteosarcoma samples." (PMID 31130627, 2019). "Although the tumor-suppressive function of SETD2 is well established in cancers such as renal cell carcinoma and leukemia, its role in osteosarcoma is still being uncovered." (PMID 40507962, 2025). "As a control, we also overexpressed H3.3G34R, which is found in glioblastoma and osteosarcoma, and which inhibits both SETD2 and NSD2 only locally in cis." (PMID 36052643, 2022). "Through the loss and gain of expression experiments, the authors demonstrated that SETD2 acts as a tumor suppressor gene in osteosarcoma cell lines." (PMID 34198693, 2021). "Also in osteosarcoma, the expression of the histone methyltransferase SETD2 has been found to be downregulated in a small cohort of patients when compared with their paired normal tissues." (PMID 34198693, 2021). "SETD2 mutations have also been detected in osteosarcoma, myxoid liposarcoma (MLPS), and synovial sarcoma (SYN), although the effect of SETD2 on the biological function of osteosarcoma has not yet been reported." (PMID 37359376, 2023).
acute myeloid leukemia (12 papers, 2016 to 2025). Acute myeloid leukemia (AML) is a group of neoplasms arising from precursor cells committed to the myeloid cell-line differentiation. "SETD2, the single mediator of trimethylation of histone 3 at position lysine 36, has been reported associated with initiation progression and chemotherapy resistance in acute myeloid leukemia (AML)." (PMID 30922329, 2019). "In line with this, we recently found that shRNA- and CRISPR/Cas9-mediated loss of SETD2 led to differentiation, enhanced DNA damage and apoptosis of acute myeloid leukemia (AML) cells harboring MLL-fusions in vitro and in vivo." (PMID 30818762, 2019). "Among them, the component C13 effectively decreased H3K36me3 levels and inhibited the SETD2-dependent proliferation of two acute myeloid leukemia cell lines, prioritizing its chemotype as a viable starting point for optimized SETD2 inhibitors." (PMID 40746737, 2025). "Acute myeloid leukemia with NPM1, IDH2, and SETD2 mutations can mimic acute promyelocytic leukemia (APL) and poses a challenge for the early and accurate differentiation and diagnosis of APL with PML::RARA." (PMID 39432585, 2024). "By generating the epigenetic mark H3K36me3, SETD2 is involved in the progression of acute myeloid leukemia." (PMID 34576219, 2021). "We recently reported that the expression and activity of SETD2 is crucial for the progression of acute myeloid leukemia (AML) with MLL rearrangements." (PMID 34576219, 2021). "A 70-year-old man was diagnosed with acute myeloid leukemia with NPM1, IDH2, and SETD2 mutations." (PMID 39432585, 2024). "APL-like acute myeloid leukemia with NPM1, IDH2, and SETD2 mutations was made." (PMID 39432585, 2024). "The upregulated expression of ERG and MYCN, which are important transcription factors that are reported to be positively related to poor clinical outcomes in patients with acute myeloid leukaemia and acute lymphocytic leukaemia, seemed to induce the LSC accumulation mediated by SETD2 deficiency." (PMID 31054182, 2019). "Our recent findings have provided ample evidence for the role of SETD2 in the progression of acute myeloid leukemia (AML) with MLL rearrangements." (PMID 34576219, 2021). "In summary, our validation experiments indicate that C13 is a non-nucleoside SETD2 inhibitor with reasonable cellular potency that nominates this chemotype for further optimization as a new treatment option for acute myeloid leukemia." (PMID 34576219, 2021).
glioblastoma (11 papers, 2018 to 2024). The most malignant astrocytic tumor (WHO grade IV). "Data on the location of the tumors is limited; a study of glioblastomas found that all tumors with SETD2 mutations were located in the cerebral hemispheres." (PMID 30419952, 2018). "Also, a 60-year-old patient presented with a thalamic glioblastoma, which demonstrated a frameshift mutation in SETD2 at a 30% VAF." (PMID 30419952, 2018). "However, one SETD2-mutant astrocytoma in an older patient (#6) also harbors an EGFR mutation and lacks IDH changes, and so is in essence a “molecular glioblastoma,” in addition to radiologically showing a gliomatosis cerebri pattern of growth." (PMID 30419952, 2018). "In glioblastoma, palmitoylation of SET domain-containing 2 (SETD2), mediated by ZDHHC16, protected SETD2 from degradation." (PMID 38532349, 2024). "In EGFR-amplified glioblastoma, palmitoylation of SETD2 mediated by ZDHHC16 protects SETD2 from degradation and, thereby, facilitates its role in mediating DNA damage response and repressing cancer initiation." (PMID 37759431, 2023).
acute leukemia (10 papers, 2016 to 2025). A clonal (malignant) hematopoietic disorder with an acute onset, affecting the bone marrow and the peripheral blood. "SETD2, a frequently mutated epigenetic tumor suppressor gene in acute leukemia, is associated with chemotherapy resistance and poor patient outcomes." (PMID 40300107, 2025). "In several types of cancer (breast, renal, gastrointestinal stromal tumors, acute leukemia), underexpression and mutation of SETD2 are associated with a poor prognosis." (PMID 32674319, 2020). "Moreover, a selective enrichment of SETD2 inactivating mutation in relapsed acute leukemia indicated an association with chemoresistance." (PMID 30922329, 2019). "Studies have identified the enrichment of mutations in SETD2 in relapsed acute lymphoblastic leukemia and MLL-rearranged acute leukemia." (PMID 30922329, 2019). "As previously discussed, SETD2 is frequently mutated in AML, MLL and relapsed acute leukemia." (PMID 39591760, 2025). "Furthermore, as a novel molecular therapeutic target, SETD2 has provided new opportunities in the diagnosis and treatment of acute leukemia." (PMID 37359376, 2023).
Luscan-Lumish syndrome (10 papers, 2022 to 2025). "Trans-heterozygote models of DNMT3A and NSD1 would be useful to better understand both TBRS and SS, and the development of other related trans-heterozygote models would also be warranted [i.e. NSD1 and SET domain containing 2 (SETD2), which cause SS and Luscan-Lumish syndrome, respectively]." (PMID 40353642, 2025). "Germline heterozygous SETD2 pathogenic variants were first described in association with a Sotos-like congenital overgrowth disorder associated with macrocephaly, intellectual disability, autism and obesity [known as Luscan-Lumish syndrome (MIM:616831)]." (PMID 37166351, 2023). "A review of the clinical and genetic features of the SETD2 patient group revealed that there were phenotypic differences between patients with truncating mutations (n = 4, Luscan-Lumish syndrome; MIM:616831) and those with missense codon 1740 variants [p.Arg1740Trp (n = 4) and p.Arg1740Gln (n = 2)]." (PMID 37166351, 2023). "For example, heterozygous mutations in SETD2 have been linked to Luscan-Lumish syndrome (LLS; OMIM 616831), characterized by macrocephaly, postnatal overgrowth, ASD, developmental delay." (PMID 40469903, 2025). "Since then, the syndrome has been officially named Luscan-Lumish syndrome (LLS), also known as “SETD2-related overgrowth syndrome”." (PMID 36777730, 2023). "Luscan-Lumish syndrome (LLS, OMIM: 616831), as a rare condition characterized by overgrowth, macrocephaly, obesity, type I Chiari malformation, and linguistic retardation, has been recognized over the recent years as an autosomal dominant genetic condition caused by SETD2 gene variant." (PMID 36777730, 2023).
acute lymphoblastic leukemia (9 papers, 2016 to 2025). Leukemia with an acute onset, characterized by the presence of lymphoblasts in the bone marrow and the peripheral blood. "Two of the genes associated with the MMR pathway, MSH6 and SETD2, were among the genes found to be frequently mutated in relapsed or therapy resistant ETV6/RUNX1 acute lymphoblastic leukemia (ALL)." (PMID 36672189, 2023). "In relapsed pediatric acute lymphoblastic leukemia (ALL) patients, SETD2 mutations were found at an increased frequency, highlighting a possible role of SETD2 in chemotherapy resistance." (PMID 34576219, 2021). "Finally, alterations in the SETD2 gene were significantly enriched in relapsed pediatric acute lymphoblastic leukemia (ALL) patients, pointing towards a potential role of SETD2 mutations in chemotherapy resistance." (PMID 30818762, 2019). "Focal deletions of SETD2 were identified in 10% of patients suffering from early T-cell precursor acute lymphoblastic leukemia (ETP-ALL)." (PMID 30818762, 2019).
liver cancer (9 papers, 2015 to 2023). An epithelial or non-epithelial malignant neoplasm that arises from the liver. "In DEN-induced liver cancer mouse model, the loss of SETD2 can significantly increase the number and size of liver tumors." (PMID 37359376, 2023). "Mechanistic analysis showed that, in addition to regulating the DNA damage response, SETD2 also inhibited the occurrence of liver cancer by regulating the balance of hepatic lipid metabolism." (PMID 37359376, 2023). "In liver cancer stem cells, HOTAIR reduces H3k36me3 by inhibiting the expression of SETD2 and promotes the malignant growth of human liver cancer stem cells." (PMID 37576402, 2023). "LncRNA HOTAIR can promote the malignant growth of human liver cancer stem cells by downregulating SETD2 in liver cancer stem cells." (PMID 30925672, 2019). "This study provides evidence for HOTAIR to promote tumorigenesis via downregulating SETD2 in liver cancer stem cells." (PMID 26172293, 2015). "Taken together, these observations suggest that the overexpressed HOTAIR oncogenic action was abrogated by the overexpression of SETD2 in human liver cancer stem cells." (PMID 26172293, 2015). "Herein, we demonstrate HOTAIR promotes human liver cancer stem cell malignant growth through downregulation of SETD2." (PMID 26172293, 2015). "To examine the relationship between long noncoding RNA HOTAIR and SETD2 in human primary liver cancer, we first detected the HOTAIR in 18 cases of human hepatocarocinoma tissues and their paired adjacent noncancerous tissues from the same patient by RT-PCR." (PMID 26172293, 2015). "In this study, we identify that HOTAIR promotes human liver cancer stem cell malignant growth through downregulation of SETD2, the enzyme that trimethylates histone H3 lysine 36 (H3K36me3), is required for ATM activation upon DNA double-strand breaks (DSBs)." (PMID 26172293, 2015). "In the 18 cases of human primary liver cancer, HOTAIR upexpression(100%) was negatively associated with the SETD2 down expression(100%) (Correlation coefficient, R = −1)." (PMID 26172293, 2015). "Gene set enrichment analysis (GSEA) revealed upregulation of several oncogenic pathways upon SETD2 loss, including the KRAS transcriptional signature, the PTEN-loss transcriptional signature, and PRC2-repressed targets identified in liver cancer, and malignant peripheral nerve sheath tumors (MPNST)." (PMID 36810256, 2023). "LncRNA HOTAIR may promote malignant progression of liver cancer by downregulating SETD2 expression and phosphorylation levels, leading to the suppression of DNA damage repair." (PMID 37686677, 2023). "The present study depicts a novel provides evidence for HOTAIR to play tumorigenesis roles by downregulating SETD2 in liver cancer stem cells, which may have potential therapeutic significance." (PMID 26172293, 2015). "It provides evidence for HOTAIR to play tumorigenesis roles via downregulating SETD2 in liver cancer stem cell, which may have potential therapeutic significance." (PMID 26172293, 2015). "The inhibition of SETD2’s phosphorylation by long non-coding RNA HOTAIR has been reported to trigger a reduction of trimethylation on histone H3 thirty-sixth lysine, consequently promoting human liver cancer stem cell malignant growth." (PMID 28390392, 2017). "Given that there was negatively correlation between the expression of HOTAIR and STED2 in human primary liver cancer, we had reasons to consider whether HOTAIR influence on the SETD2 expression and its modification." (PMID 26172293, 2015). "Although reduction of SETD2 may partly contribute to HOTAIR-medicated promotion of liver cancer stem cell growth, our findings in this study provide novel evidence for an active role of SETD2 in HOTAIR-mediated promotion of liver cancer stem cell growth." (PMID 26172293, 2015).
melanoma (9 papers, 2019 to 2025). A malignant, usually aggressive tumor composed of atypical, neoplastic melanocytes. "To further explore the underlying mechanisms of SETD2 downregulation in melanoma, we analyzed the significant different genes and evaluated the pathways in which SETD2 may involve using TCGA-SKCM samples." (PMID 38843391, 2024). "The study focusing on SETD2 dysfunction in melanoma proves that SM patients having this feature are directed toward immunotherapy as first therapeutical line." (PMID 41470117, 2025). "To verify the predicting value of SETD2 alteration in immunotherapy response in melanoma, we created a nomogram based on 320 melanoma patients who underwent immunotherapy from MSKCC." (PMID 38843391, 2024). "Our results showed that SETD2 expression in melanoma samples was significantly correlated to melanogenesis, skin and epidermal cells development pigment or melanin metabolic process." (PMID 38843391, 2024). "This study provides novel insights into the functional role of SETD2 in melanoma, highlighting a potential mechanism whereby SETD2 influences the prognosis of melanoma patients as well as therapeutic response." (PMID 38843391, 2024). "SETD2 was found down-regulated in melanoma samples corroborated with an unfavorable survival rate." (PMID 41470117, 2025). "SETD2 knock-out A375 cell line (A375SETD2ko) was developed by Crispr/cas9 and CCK-8 analysis and nude mice used to evaluate the proliferation and invasion of melanoma cells in vitro and in vivo, while Western blotting tested the MMR-related protein." (PMID 38843391, 2024).
metastatic disease (8 papers, 2015 to 2025). "Notably, BRCA2 mutations were significantly enriched in metastatic tumors (9.3% vs. 0%; p = 0.0138), as were SETD2 mutations (11.1% vs. 1.5%; p = 0.0411)." (PMID 39941902, 2025). "The role of SETD2 mutation in metastatic disease therefore remains to be fully elucidated." (PMID 36510186, 2022). "In an attempt to identify druggable targets in these lesions, we undertook an in-depth analysis of the mutational profiles of the primary and metastatic tumor tissues, which revealed a novel SETD2 mutation whose molecular effects were documented by in vitro studies." (PMID 32674319, 2020). "In large ccRCC cohorts, SETD2 is among the most recurrently altered tumor-suppressor genes (≈10–15% in primaries) and appears further enriched in metastatic disease (≈30%), underscoring its role in progression." (PMID 41440218, 2025). "Comparison of the primary and metastatic tumors revealed that PPP2R1A (E370X), SETD2 (I1608V), SMAD4 (G382T), and AR splicing site mutations may be specific to liver metastatic cancer." (PMID 27023146, 2016).